PRF1 (perforin 1)
Diseases named in the same sentence as PRF1 in open-access papers (continued):
Sharing a sentence is not in itself a finding about the gene and the disease.
leishmaniasis (1 paper, 2021). Infectious disease that is transmitted through the bite of hematophagous female phlebotomine sand flies. "Interestingly, VL patients also exhibit higher expression of GZMA, GZMB, and PRF1 in the blood compared to healthy subjects, indicating a potential common cytolytic response in leishmaniasis." (PMID 33793565, 2021).
liver failure (1 paper, 2018). A liver disease characterized by the liver losing or has lost all of its function. "If so, pharmacological inhibiton of perforin-1 may be helpful in patients with a high risk of developing fulminant viral hepatitis to prevent further disease aggravation and transition into liver failure." (PMID 30442932, 2018). "The severe sinusoidal perfusion deficits of the liver resulting from antigen-specific CD8 T cell effector function against LSECs required perforin-1 as non-redundant effector mechanism and triggered liver failure." (PMID 30442932, 2018).
lower respiratory tract infections (1 paper, 2020). "Risk of severe lower respiratory tract infections, including HRSV, has been associated with increased DNA methylation at birth in the enhancer region of PRF1, which encodes perforin-1, an important mediator of CD8+ T cell and NK T cell-mediated cytotoxicity." (PMID 32887352, 2020).
lymphopenia (1 paper, 2018). Reduction in the number of lymphocytes. "In contrast, DEGs found exclusively during EBOV infection were mostly involved with dysregulation of blood circulation and vasculature development as well as lymphopenia as evidenced by a decrease in CD79B, CD3, CD8, NFATC3, and PRF1." (PMID 30723475, 2018).
lymphoproliferative disorders (1 paper, 2019). "Nearly 58% FHL cases are reported to harbour mutations in PRF1 gene (located at 10q22.1) that alters the normal function of perforin; whereas 40–60% of all X-linked lymphoproliferative disorders harbour mutation in SLAM-associated protein (SAP) regulating gene SH2D1A (located at Xq25)." (PMID 30849948, 2019).
mesenchymal tumors (1 paper, 2025). "A dot plot revealed a progressive decrease in both expression levels and the proportion of NK cells expressing canonical cytotoxic and trafficking-associated genes (Gzma, Gzmb, Prf1, Cxcr6) from epithelial to mesenchymal tumors." (PMID 41280107, 2025).
myocarditis (1 paper, 2025). Myocarditis is a condition that is characterized by inflammation of the heart muscle (myocardium). "TCR sequencing revealed expansions of CD8 GZMK + GZMA + and CD8 PRF1 + GZMA + T cells in myocarditis patients, along with increased activation markers CD69 and KLRG1, supporting the idea that specific cytotoxic CD8 T cell groups promote inflammation." (PMID 41510228, 2025). "Of particular significance, at baseline, patients who manifested irAEs with myocarditis were characterized by considerably higher concentrations of CD8 PRF1 + T cells compared to those who did not experience myocarditis." (PMID 41510228, 2025).
myositis (1 paper, 2022). "Indeed, we previously showed that deleting PRF1 reduced the severity and incidence of myositis in C protein–induced myositis (CIM), a mouse model of PM6." (PMID 35013338, 2022).
Neonatal sepsis (1 paper, 2025). Systemic inflammatory response to infection in newborn babies. "These include a fatal neonatal FHL2 with compound PRF1 variants and absent perforin expression, and an early-infant FHL2 that presented as late-onset neonatal sepsis before genetic confirmation." (PMID 41477640, 2025).
ovarian endometriosis (1 paper, 2023). A non-neoplastic disorder characterized by the growth of endometrial tissue in the ovaries. "Specifically, the expression of KIR2DL4 was remarkably downregulated, while the expressions of PROK1, IGFBP1, RBP4, G2MB, KIR3DL1, and PRF1 were significantly upregulated in ovarian endometriosis." (PMID 37662927, 2023).
parasitemia (1 paper, 2016). "Despite their effective control of parasitemia, about 80% of infected Prf1-/- mice developed ruffled fur by 70 days after infection." (PMID 27403737, 2016).
prostate tumors (1 paper, 2023). "PCa tissues obtained from RP displayed almost no expression of Granzyme-B (GZMB) and Perforin 1 (PRF1), markers of cytolytic activity, indicating that T cells infiltrating prostate tumors are functionally impaired." (PMID 37090711, 2023).
rectal cancer (1 paper, 2022). A primary or metastatic malignant neoplasm that affects the rectum. "Gene expression levels of GZMA, GZMB, PRF1, IFNG and chemokine CXCL10 were compared between responsive versus non-responsive rectal cancer patients." (PMID 35534879, 2022).
renal carcinoma (1 paper, 2011). A carcinoma arising from the epithelium of the renal parenchyma or the renal pelvis.
retinal degeneration (1 paper, 2023). Degeneration of the retina. "Specific inhibitors of the Prf1 pathway, already in preclinical studies for non-ocular diseases, may also provide novel strategies to stop these early events associated with the development of retinal degeneration." (PMID 37689689, 2023). "In conclusion, our data suggest a critical function of Prf1-mediated T-cell neurotoxicity during retinal injury, indicating that targeting infiltrating Prf1+ and CD8+ T cells may be a potential treatment for retinal degeneration." (PMID 37689689, 2023).
RSV bronchiolitis (1 paper, 2017). "We observed a reduction in blood DNA methylation of the PRF1 proximal enhancer in children in association with previous hospitalisation for severe RSV bronchiolitis during infancy." (PMID 28253869, 2017).
sarcoidosis (1 paper, 2025). Sarcoidosis is a multisystemic disorder of unknown cause characterized by the formation of immune granulomas in involved organs. "By contrast, T cells from sarcoidosis patients exhibited clonal expansion of terminally differentiated CD8+ effectors that expressed high levels of effector genes, including CCL5, GZMB, PRF1, IFNG, KLRG1 and ZEB2." (PMID 40469525, 2025).
skin infection (1 paper, 2019). An inflammatory process affecting the skin, caused by bacteria, viruses, parasites, or fungi. "Following VacV-OVA skin infection, H2-Kb-OVA257-264 specific memory CD8+ T cells expanded slightly more in LM-OVA immune Prf1-/- mice compared to WT controls, but provided less protection against the virus." (PMID 30875408, 2019).
trypanosomiasis (1 paper, 2016). Infection with protozoa of the genus trypanosoma. "Despite the dramatic decrease in trypanosomiasis pathology in infected Prf1-/- mice compared to infected intact mice, perforin gene deletion is not proposed as a practical approach to generate trypanosomiasis-resistant mammals." (PMID 27403737, 2016).
uveitis (1 paper, 2023). An inflammatory process affecting a part of or the entire uvea. "In contrast, uveitis in the BD patient had few of these effector CD4+ T cells but was characterised by clonally expanded effector CD8+ T cells expressing CCL5, GZMA, GZMB and PRF1." (PMID 37720629, 2023).
viral encephalitis (1 paper, 2014). Encephalitis resulting from viral infection. "VV challenge, Prf1 deficient mice succumbed to viral encephalitis." (PMID 24606807, 2014).
viral hepatitis (1 paper, 2018). An acute or chronic inflammation of the liver parenchyma caused by viruses. "Using a novel pharmacological perforin-1 inhibitor, we demonstrate that blocking perforin-1 function rescues mice with viral hepatitis from fulminant liver failure, which may provide a salvage treatment strategy for patients with fulminant viral hepatitis." (PMID 30442932, 2018).
tumor (315 papers, 1991 to 2026). "To investigate the mechanism underlying tumor control in Prf1–/–MMTV-PyMT mice treated with the HO inhibitor SnMP, we analyzed tumors 36 hours after the initiation of treatment to capture the earliest biological changes in the TME." (PMID 40627458, 2025). "These cells were also clearly distinct from the tumor-associated CD69+IFNG+PRF1– and the dysfunctional/low cytotoxic NR4A1+ CD158a (KIR2DL1)+ CD158e (KIR3DL1)+ NK cell populations described in the other studies." (PMID 40530504, 2025). "The cytolytic activity defined as the geometric mean of GZMA and PRF1 expression value is associated with anti-tumor immune response and prognosis." (PMID 40556672, 2025). "Using animal and human models of MMRd, we determined that interactions between MHC+ C1Q+ CXCL9+ macrophages and TCF+ BHLHE40+ PRF1+ T cell subsets are associated with control of MMRd tumor growth, during anti-PD-1 treatment." (PMID 40027748, 2025). "For instance, miR-30e was shown to suppress translation of PRF1, encoding perforin, and impair NK killing of tumor targets." (PMID 40647470, 2025). "Genes associated with increased cytotoxicity (GZMB, GNLY, PRF1), and anti-tumor activity (NKG7) were upregulated in the cytotoxic lymphocytes, including CD8 + T cells, γδ T cells, NK cells, and ILCs." (PMID 41194247, 2025). "Above-median expression of GZMB and PRF1 in tumor at progression was also associated with longer median OS (42 months vs. 13 months and 42 months vs. 11 months, respectively)." (PMID 40239619, 2025). "DNA hypermethylation in PRF1 is associated with increased PD-1 expression in tumor tissue-resident memory cells, indicating the exhaustion of the immune function." (PMID 35163049, 2022). "The engagement of NKG2D with its ligands expressed on tumor cells likely facilitates tumor killing by Cbx3/HP1γ-deficient CD8+ effector T cells through the enhanced production of PRF1, GrB and INF-γ." (PMID 34721405, 2021). "In vivo, c-FLIP overexpression protected tumor cells from lysis by NK cells in a PRF1-deficient murine model, once again highlighting the importance of this protein in cancer." (PMID 32466293, 2020). "To determine the role of both helper and cytotoxic activities of Trp1 cells in tumor rejection, we transferred either Trp1 or perforin-1-deficient Trp1 cells (Prf1−/−Trp1) into wild-type (WT) or Ifngr1−/− hosts combined with radiation and αCTLA-4." (PMID 31924474, 2020). "Prf1−/−Trp1 cells transferred to IFN-γR-deficient were unable to control tumor growth, confirming that both Th1 and cytotoxic activities of Trp1 cells (Trp1 Th-ctx) are critical for maximal tumor control." (PMID 31924474, 2020). "To test the involvement of this pathway in CBLB502-stimulated tumor clearance, we challenged perforin-deficient (Prf1−/−) mice with RMAS cells." (PMID 24454895, 2014). "Although the cause of the heightened type I IFN response in Prf1–/– tumors remains unclear, it may contribute to the delayed tumor onset observed in these mice, suggesting incomplete suppression of this response by HO-1." (PMID 40627458, 2025). "Moreover, there was reduced expression of PRF1 and NK cytotoxicity genes in tumor-infiltrating NK cells versus adjacent normal colorectal tissue, further suggesting a loss of anti-tumor NK cell function." (PMID 38267402, 2024). "The PRF1 gene encodes a protein that forms pores and is critical for granzyme-induced programmed cell death and for protecting against cells infected by viruses or affected by neoplasia." (PMID 39650642, 2024). "Subsequently, the tumor organoids were treated with anti‐PD‐1 and anti‐PD‐L1 agents, and the mRNA expression levels of crucial markers (granzyme B, perforin 1, and IFN‐γ) associated with tumor‐infiltrating T cell proliferation and activation were meticulously assessed." (PMID 38815251, 2024). "Loss or reduction in PRF1 expression may weaken the anti-tumor immune response, which may make it easier for tumor cells to grow and spread." (PMID 39199299, 2024).
tumor (continued). "In general, PRF1 deficiency may weaken the antitumor immune response, causing tumor cells to evade recognition by the immune system and avoid attack." (PMID 39199299, 2024). "Interestingly, the expression of the toxins granzyme A (GZMA) and Perforin 1 (PRF1), secreted by effector cytotoxic T cells and natural killer (NK) cells, were recently shown to be linked to intra-tumoural immune cytolytic activity." (PMID 38022682, 2023). "In C57BL/6 mice, the difference in tumour incidence between wild-type and perforin-1-deficient mice drops from 0.8 with a dose of 25 μg 3-MCA to 0.2 with a dose of 100 μg 3-MCA, whereas in 129/SvEv mice the difference is stable at doses of 25 and 100 μg 3-MCA (0.26 and 0.29, respectively)." (PMID 19638986, 2009). "PRF1 expression is generally associated with a better prognosis in certain cancers, including melanoma, lung, breast, and colorectal cancers, where it indicates a strong anti-tumor immune response, which may inhibit tumor growth and spread." (PMID 39199299, 2024). "Furthermore, PRF1 deficiency may result in alterations to the tumor microenvironment, such as the upregulation of immunosuppressive factors such as TGF-β and IL-10." (PMID 39199299, 2024). "Interestingly, mice carrying lymphoma and deficient for a gene (Hif1a) coding for a transcription factor useful for hypoxia adaptation also show reduced tumor growth in association with an increase in activated tumor-infiltrating NK cells (high expression of Ifng, Cd69, Prf1, Gzma and Gzmb)." (PMID 34680190, 2021). "Gene signatures associated with NK‐cell cytotoxicity and activation (Gzma, Prf1, Klrd1, Nkg7, and Klrk1) were markedly upregulated at high proportions of NK cells in nanoSTING@Mn combined with LLL on dLNs and Tumor, as compared to nanoSTING@Mn alone (bottom)." (PMID 41126739, 2026). "They showed enhanced tumor cell-killing activity in a dose- and time-dependent manner while activating multiple signaling pathways, including granzyme–PRF1–PARP, Fas–FADD–caspase, and IFN-γ pathways." (PMID 40281554, 2025). "Tumor control in Prf1–/–MMTV-PyMT mice treated with SnMP was dependent on CD8+ T cells and NK cells but independent of their expression of perforin or IFN-γ." (PMID 40627458, 2025). "Smart, biocompatible nanoparticles can be engineered to precisely deliver extracellular-acting PFPs (e.g., PRF-1 and granulysin) directly to tumor sites or to regulate the expression and activation of intracellular PFPs (e.g., GSDMs and MLKL)." (PMID 40691738, 2025). "Among the DEGs, genes expressed at higher levels in RARα‐KO CTLs included major effector molecules required for anti‐tumor immunity, such as Ifng, Gzmb, and Prf1." (PMID 40068101, 2025). "GZMB and PRF1 showed consistently elevated expression in tumor samples compared to normal tissues across several cancers, such as BRCA and KIRC, suggesting their role in tumor immune activity." (PMID 40002821, 2025). "To identify the cellular source of Ifnb1 expression in the TME, we used RNAscope on Prf1–/–MMTV-PyMT tumor sections." (PMID 40627458, 2025). "PRF1 plays important roles in various aspects of tumor cell development, immune escape mechanisms, cancer immunotherapy, and prognosis." (PMID 41048344, 2025). "To assess the functional relevance of type I IFN signaling in this TME, we treated tumor-bearing Prf1–/– mice with a neutralizing antibody against IFNAR1, a subunit of type I IFN receptor." (PMID 40627458, 2025). "Cytotoxic/effector genes (GNLY, GZMA, GZMK, IFNG, NKG7, PRF1) were primarily expressed by T and NK cells, with notable upregulation in stRNA‐seq‐defined invasive front and tumor core regions." (PMID 41057994, 2025). "Through spatial and molecular profiling, they found that CD8+ cytotoxic T cells in tumor-rich regions expressed effector molecules such as PRF1, GZMK, and TNF, indicating preserved cytotoxic function." (PMID 41001043, 2025).
tumor (continued). "On the contrary, it was negatively correlated with cytokine‐encoding related genes such as IFNG, GZMB, PRF1, and TNF in most tumor types." (PMID 40013761, 2025). "Third, tumor subsets enriched for immune markers, including cytotoxic immune genes (e.g., Prf1, Gzmb, Gzmg) and mast cell protease genes (e.g., Mcpt1, Cma1, Tpsb2)." (PMID 40171265, 2025). "These cells exhibited a higher percentage of the key cytotoxic molecule perforin-1 (PRF1), indicating an activated anti-tumor immune response in this population." (PMID 40411616, 2025). "The main TCR clones, overexpressing PRF1, appeared to be enriched between the T cell enriched and the T cell excluded zones, suggesting that they drive the anti-tumor response." (PMID 40027748, 2025). "Early stages of tumor growth were marked by robust T cell activation, including expression of cytotoxic mediators such as PRF1, GZMB, and IFN-γ, and dynamic polarization supported by IL-12 and STAT4." (PMID 41278869, 2025). "Existing research indicates that PRF1 (perforin) expression correlates with multiple factors and plays a pivotal role in regulating tumor immune networks." (PMID 40411616, 2025). "Our analysis revealed significant correlations between GZMA, GZMB, GZMK and PRF1 expression and cytotoxic T cell infiltrates across various cancer types, underscoring the crucial roles of these genes in modulating the tumor microenvironment." (PMID 40002821, 2025). "To investigate a potential functional role of CD8+ T cells and NK cells in the tumor control observed in Prf1–/–MMTV-PyMT mice, we performed in vivo depletion of these cell populations prior to SnMP treatment." (PMID 40627458, 2025). "Overall, our results demonstrate that CAR-CLDN18.2 γδ T cells can effectively recognize CLDN18.2-positive target tumor cells and secrete high levels of Granzyme-B, Perforin-1, and IFN-γ to exert antitumor effects." (PMID 40149332, 2025). "CYT, calculated as the geometric mean of GZMA and PRF1 mRNA expression in tissue, generally indicates a stronger anti-tumor immune response and heightened sensitivity to immune checkpoint inhibitors, reflecting the host’s immune status." (PMID 40276654, 2025). "In comparison to the adjacent non-tumor tissues, the CD56dimCD16hi NK cells within tumors showed a decrease in the expression of cytotoxic effector genes, such as PRF1 and most granzymes (GZMA, GZMH, and GZMM), except for GZMB." (PMID 38552055, 2024). "These treatments can indirectly increase the role of PRF1 because they enable CTLs and NK cells to attack tumor cells more aggressively, thereby increasing PRF1-mediated killing." (PMID 39199299, 2024). "PRF1 plays an important role in various aspects of tumor cell development, immune escape mechanisms, immunotherapy for cancer, as well as prognosis." (PMID 39199299, 2024). "We tested the protein expression of some of these genes and others associated with T and NK cell cytotoxicity (CD4, CD8, IFN-γ, Perforin 1, and NKp46) via immunofluorescence imaging within the tumor sections." (PMID 39703517, 2024). "In tumor cells and non-tumor cells, PRF1 acts under physiological as well as pathological conditions, and increasing evidence suggests that PRF1 secretion can form pores in tumor cell membranes, resulting in tumor cell lysis and death." (PMID 39199299, 2024). "The CD56dimCD16hi subsets of NK cells within the tumor tissue showed lower expression levels of cytotoxic genes like PRF1, GZMB, GZMA, GZMH, and GZMK compared to normal tissues." (PMID 38552055, 2024). "PRF1 and GZMB encode pore-forming and cytotoxic granules, respectively, involved in the cytotoxic process of NK and T cells against tumor cells." (PMID 39502689, 2024). "The role of PRF1 in cancer prognosis is complex and depends on a number of factors, including the type of cancer, PRF1 expression levels, the tumor microenvironment, and the overall health of the patient." (PMID 39199299, 2024).